LRRC26 (leucine rich repeat containing 26)
Description:
Auxiliary protein of the large-conductance, voltage and calcium-activated potassium channel (BK alpha). Required for the conversion of BK alpha channels from a high-voltage to a low-voltage activated channel type in non-excitable cells. These are characterized by negative membrane voltages and constant low levels of calcium.
Synonyms: CAPC; bA350O14.10; OTTHUMG00000020980
Tractability: Small molecule: a structure with a bound ligand is known; it belongs to a druggable protein family. Antibody: its Gene Ontology location is reachable by antibodies, with high confidence; UniProt places it where antibodies can reach, with medium confidence; UniProt predicts a signal peptide or a membrane-spanning region; the Human Protein Atlas places it where antibodies can reach.
Gene: Protein-coding gene on chromosome 9 (137,168,758 to 137,170,051, reverse strand). Ensembl gene ENSG00000184709.
Subcellular location: Cell membrane; Cytoplasm, cytoskeleton
Subcellular location (Human Protein Atlas): Plasma membrane; Nucleoli fibrillar center
Gene Ontology:
Molecular function: potassium channel activator activity; potassium channel regulator activity; protein binding; transmembrane transporter binding; voltage-gated potassium channel activity
Biological process: positive regulation of voltage-gated potassium channel activity; potassium ion transmembrane transport
Cellular component: extracellular exosome; plasma membrane; voltage-gated potassium channel complex; cytoskeleton
Genetic constraint (gnomAD): Loss-of-function variants: 18 observed, 6.4 expected, observed/expected ratio (o/e) 2.81. That is too few expected variants to judge how well the gene tolerates losing a copy. Missense variants: 573 observed, 305.04 expected, observed/expected ratio (o/e) 1.88, 90% interval 1.75 to 1.98. Synonymous variants: 301 observed, 162.22 expected, observed/expected ratio (o/e) 1.86, 90% interval 1.68 to 1.98.
Homologues: Orthologues: chimpanzee LRRC26 (99% identical), macaque LRRC26 (96% identical), pig LRRC26 (73% identical), dog LRRC26 (72% identical), mouse Lrrc26 (67% identical), rat Lrrc26 (66% identical), guinea pig LRRC26 (62% identical), Caenorhabditis elegans sma-10 (22% identical), Drosophila melanogaster kek3 (22% identical), Drosophila melanogaster CG18095 (22% identical), Drosophila melanogaster Con (21% identical), zebrafish lgi1b (20% identical), and 5 more. Paralogues in human: TRIL (29% identical), LRIG1 (28% identical), CHADL (28% identical), LRIG3 (28% identical), LGR6 (27% identical), LRIG2 (27% identical), LRRC24 (27% identical), LGR5 (26% identical), CPN2 (25% identical), LRG1 (23% identical), LGR4 (22% identical), LRRTM2 (22% identical), and 10 more.
Diseases named in the same sentence as LRRC26 in open-access papers:
LRRC26 is named in the same sentence as 10 diseases in open-access papers, as found by Europe PMC text mining. Sharing a sentence is not in itself a finding about the gene and the disease. The quoted sentences say what the papers report.
breast carcinoma (3 papers, 2014 to 2023). "Overexpression of LRRC26 in breast cancer inhibits NF-κB activity and suppresses tumorigenesis and lung metastasis." (PMID 37525118, 2023). "The expression levels of LRRC26 transcripts in metastatic breast cancer tissue were significantly higher than those in the primary tumor." (PMID 29713287, 2018). "Similar to KCa1.1-expressing prostate cancer cells, LRRC26 was the main auxiliary subunit of KCa1.1 in KCa1.1-expressing breast cancer MDA-MB-453 cells (vehicle) and breast cancer tissues." (PMID 29713287, 2018). "On the other hand, Nfkb activation could be suppressed in the lung tumors of MS-exposed mice due to the overexpression of Lrrc26, which has also been shown to occur in the breast cancer cell line MDA-231 and the epidermoid cancer cell line A431." (PMID 26109882, 2014). "On the other hand, the auxiliary γ 1 subunit, LRRC26, which activates KCa1.1 via a large negative shift in voltage dependence, is mainly expressed in MDA-MB-453 cells and breast cancer tissues." (PMID 29713287, 2018).
cystic fibrosis (2 papers, 2017 to 2021). Autosomal recessive disorder caused by pathogenic variants in the CFTR gene (cystic fibrosis transmembrane conductance regulator), which encodes a chloride and bicarbonate channel expressed in epithelial cells, and follow the diagnosis criteria. "In addition, downregulation of LRRC26 (γ1) and subsequent reduction of BKCa function have also been shown in cystic fibrosis bronchial epithelial cells." (PMID 34827626, 2021). "In cystic fibrosis patients, TGF-β1 is elevated and interferes with the expression of LRRC26." (PMID 34827626, 2021).
prostate carcinoma (2 papers, 2014 to 2018). A carcinoma that arises from epithelial cells of the prostate gland. "Meanwhile, overexpression of LRRC26 in another prostate cancer cell line, PC3, which lacks endogenous LRRC26 expression, converted the endogenous typical BKα channels to the low-voltage–activated LNCaP-type BK channels." (PMID 25360119, 2014). "In prostate cancer cells, the γ1 subunit, LRRC26 elicits a large negative shift in the voltage dependence of KCa1.1, thereby activating KCa1.1 at physiological voltages and resting intracellular Ca2+ levels." (PMID 29713287, 2018).
triple-negative breast carcinoma (1 paper, 2021). An invasive breast carcinoma which is negative for expression of estrogen receptor (ER), progesterone receptor (PR), and human epidermal growth factor receptor 2 (HER2). "LRRC26 is reported to be a negative regulator of NF-κB activity and it is downregulated in triple-negative breast cancer." (PMID 33827643, 2021).
cancer (6 papers, 2018 to 2022). A tumor composed of atypical neoplastic, often pleomorphic cells that invade other tissues. "For instance, a hypomethylation was observed in CpG sites associated with cancer-related genes: leucine-rich repeat-containing 26 (LRRC26), homeobox B9 (HOXB9), and BR serine/threonine kinase 2 (BRSK2) only in boys, which correlated with an increase in As levels." (PMID 30873799, 2018). "Studies on the function of LRRC26 gene in LNCaP cell culture have shown that its overexpression leads to suppression of the NF-κB pathway, which is involved in cancer progression and metastasis." (PMID 33552133, 2020). "There are conflicting reports on the involvement of BKγ1 (also known as LRRC26 and CAPC) in cancer." (PMID 31071485, 2019).
tumor (4 papers, 2014 to 2023). "In contrast, leucine rich repeat containing 26 (LRRC26, a tumor suppressor) was modestly decreased by either stimulus alone, whereas the combined stimuli decreased LRRC26 expression significantly." (PMID 37975243, 2023).
LRRC26 also shares sentences with these, for which no sentence is quoted: adenoma (1 paper); colitis (1); pancreatic cancer (1); rectal cancer (1).